NLRP3 (NLR family pyrin domain containing 3)
Diseases named in the same sentence as NLRP3 in open-access papers (continued):
Sharing a sentence is not in itself a finding about the gene and the disease.
glomerulonephritis (13 papers, 2011 to 2025). A renal disorder characterized by damage in the glomeruli. "This study was designed to investigate whether HBx-induced podocyte injury is related to the nucleotide-binding oligomerization domain-like receptor protein 3 (NLRP3) inflammasome and the specific mechanism of the oxidative stress pathway in hepatitis B virus-associated glomerulonephritis (HBV-GN)." (PMID 35656447, 2022). "demonstrates that in a model of anti-glomerular basement membrane crescentic glomerulonephritis, endogenous glomerular cells cannot induce glomerulonephritis through the NLRP3–ASC–caspase-1 axis." (PMID 41357229, 2025). "Here, we also observed a statistically significant increase in IL-1β serum level of glomerulonephritis-HD patients which can further support the activation of the NLRP3-ASC-caspase-1 axis in these patients." (PMID 34904012, 2021). "Only one study has previously reported a positive correlation between NLRP3 expression and proteinuria in patients with glomerulonephritis; however, patients with several types of primary glomerular disease were included in that study." (PMID 31796125, 2019). "This may be related to the release of high-mobility group protein 1 in an NLRP3-mediated manner during glomerular nephritis, highlighting the complexity of NLRP3’s role in kidney diseases." (PMID 41357229, 2025). "However, the mechanism involved in NLRP3 inflammasome activation in the PBMC derived from glomerulonephritis-HD patients remains to be investigated." (PMID 34904012, 2021). "Numerous studies have demonstrated that the NLRP3 inflammasome is a key mechanism involved in the development of a wide variety of human kidney diseases, including AKI, CKD, glomerulonephritis, and obesity-related kidney disease." (PMID 38720901, 2024). "Together, genes that are related to the NLRP3-ASC-caspase-1 axis are induced during progressive glomerulonephritis but only in the tubulointerstitium and not in the glomerular compartment of the kidney." (PMID 22046355, 2011). "However, no study has been investigated the role of NLRP3 and NLRC4 inflammasomes in inflammation associated with hemodialysis in patients suffered from glomerulonephritis." (PMID 34904012, 2021).
multiple myeloma (13 papers, 2018 to 2025). "In multiple myeloma patients with a mutation in CARD8 (a negative regulator of NLRP3 inflammasome) had a significantly higher percentage of pro-inflammatory Th1 cells." (PMID 31379813, 2019). "We also investigated the relationship between the genetic polymorphism of the NLRP3 inflammasome and Th cells in multiple myeloma." (PMID 30211233, 2018). "However, there is no data on the association of the genetic polymorphism of the NLRP3 inflammasome with Th subsets in multiple myeloma." (PMID 30211233, 2018). "Therefore, the genetic polymorphisms of the NLRP3 inflammasome associated with Th cells might be involved in the pathogenesis of multiple myeloma, which needs further study in the future." (PMID 30211233, 2018). "Therefore, the genetic polymorphisms of the NLRP3 inflammasome associated with Th cells might be involved in the pathogenesis of multiple myeloma." (PMID 30211233, 2018). "The involvement of the NLRP3 inflammasome has been also recently appreciated in multiple myeloma progression, where an abundance of β2-microglobulin in the serum drives TAMs-derived NLRP3 speck formation and pro-inflammatory cytokines release." (PMID 37891577, 2023). "In multiple myeloma, the pro-tumoral effect of IL-18 was shown to be due of its release in a NLRP3-dependent from TAMs and favored the immunosuppressive activity of MDSCs." (PMID 37298187, 2023). "In either in vitro or in vivo experiments, administration of NLRP3 inhibitors caused amelioration of the disease burden in AML, DLBCL, GvHD, multiple myeloma, and sickle cell anemia." (PMID 35897704, 2022). "In fact, proximity ligation assays confirmed the co-localization of ASC specks with NLRP3 in myeloma cells." (PMID 33066043, 2020). "The pathogenesis of multiple myeloma (MM) remains unclear and the NLRP3 inflammasome has been more and more recognized in the progression of many diseases." (PMID 30211233, 2018). "It is known that the administration of the NLRP3 inhibitors reduced the severity of the disease in AML, DLBCL, GvHD, multiple myeloma, and sickle cell anemia in both vitro and in vivo studies." (PMID 36902299, 2023). "In two separate myeloma cell lines, we observed significant PLA signals for ASC colocalized with NLRP3 after 8 h of D089 treatment." (PMID 33066043, 2020).
pancreatic ductal adenocarcinoma (13 papers, 2020 to 2025). An infiltrating adenocarcinoma that arises from the epithelial cells of the pancreas. "While the nucleotide‐binding oligomerization domain (NOD)‐like receptor pyrin domain containing 3 (NLRP3) inflammasome pathway's role in pancreatic ductal adenocarcinoma (PDAC) has been extensively studied, its implications in IPMN remain unexplored." (PMID 39969214, 2025). "The NLRP3 signaling pathway promoted the expansion of immunosuppressive macrophages, thereby promoting tumor growth in pancreatic ductal adenocarcinoma." (PMID 38116060, 2023). "In Liu’s study, NLRP3 was reported to be upregulated in pancreatic ductal adenocarcinoma (PDA), as shown in both infiltrating immune cells and tumor cells; and the activation of NLRP3 inflammasome in macrophages would induce immunological tolerance and promote the tumor growth." (PMID 36619871, 2022).
renal cell carcinoma (13 papers, 2019 to 2025). "As a natural compound, ursolic acid upregulates expression of NLRP3 in RCC and then activates caspase-1, which eventually causes prolapse of renal cell carcinoma and inhibits tumour growth." (PMID 36702978, 2023). "This approach of increasing anti-PD-1 efficacy has been validated in pre-clinical experimental models in metastatic melanoma and renal cell carcinoma through modulating PD-L1 expression downstream of NLRP3 activation." (PMID 35631400, 2022). "The expression of NLRP3 inflammasome was up-regulated in renal cell carcinoma compared with the normal kidney tissue." (PMID 30770793, 2019). "According to our research, we considered that the LXRα and NLRP3 inflammasome had the possibility to be novel therapeutic targets in renal cell cancer." (PMID 30770793, 2019). "In Brief, LXRα had the possibility to be a novel diagnostic and prognostic biomarker and therapeutic target in renal cell cancer and LXRα could regulate the metastasis of renal cell cancer via NLRP3 inflammamsome." (PMID 30770793, 2019). "Recently, JQ1 has been shown to induce pyroptosis in renal cell carcinoma (RCC) via the activation of NF-κB, which subsequently activates the NLRP3 inflammasome, leading to caspase-1-dependent pyroptosis." (PMID 40149884, 2025).
urticaria (13 papers, 2019 to 2025). A vascular reaction of the skin characterized by erythema and wheal formation due to localized increase of vascular permeability. "Based on the sequencing results and the presence of unprovoked generalized inflammation, including recurrent fever, urticaria-like rashes, aseptic meningitis, and sensorineural hearing loss, NLRP3-AID was determined to be the most likely diagnosis." (PMID 40852416, 2025). "According to recent reports, there is a strong correlation between NLRP3 and the onset of urticaria." (PMID 39081309, 2024). "In conclusion, our literature review on CAPS patients shows that patients displaying pathogenic NLRP3 variants in the LRR domain present with more hearing loss and less frequent cutaneous urticaria lesions compared to patients with classical CAPS." (PMID 39195255, 2024). "NLRP3-associated autoinflammatory diseases (NLRP3-AID) are rare genetic autoinflammatory diseases characterized by chronic inflammation and an urticaria-like rash." (PMID 36510304, 2022). "For example, the patient’s cold-induced urticaria-like rash, fever, arthralgia, and progressive SNHL, accompanied by enhanced monocyte NLRP3 signaling and IL-1β production, corresponded with the features of disorders caused by autosomal dominant NRLP3 gain-of-function mutations." (PMID 41168503, 2025). "Based on the clinical presentation, laboratory findings, and sequencing results of our patient—particularly her neonatal onset of aseptic meningitis and urticaria-like rashes without specific cold exposure—severe NLRP3-AID (NOMID) was considered the most appropriate diagnosis." (PMID 40852416, 2025). "This case highlights unique manifestations of NLRP3-AID, namely the absence of urticaria-like rash, eosinophilic organ infiltration, and pseudoseptic serositis." (PMID 36510304, 2022).
Atrophy (12 papers, 2017 to 2026). Any weakening or degeneration, especially through lack of use. "For example, NLRP3 inflammasome activation causes age-related thymic atrophy and immunosenescence, while deletion of NLRP3 and ASC in inflammasome assembly rescues the age-related thymic demise, increases T cell progenitors, and alleviates immune senescence." (PMID 41299782, 2025). "While NLRP3 has been recognized as a vital regulator of skeletal muscle metabolism and implicated in the pathogenesis of muscle atrophy, its specific role in diabetic muscle atrophy remains unclear." (PMID 38338456, 2024). "For the activation of the NLRP3 inflammasome in the case of muscle atrophy, angiotensin II can increase mitochondrial dysfunction and the production of ROS within the mitochondria, which in turn stimulates the NLRP3 inflammasome." (PMID 38248332, 2024). "MCC950, a specific, small-molecule NLRP3 inhibitor, has the potential to alleviate diabetic muscle atrophy by inhibiting NLRP3-mediated pyroptosis." (PMID 38338456, 2024). "In our study, NLRP3 expression was significantly reduced by the NNL-extract administration in DEX-induced atrophy in mice." (PMID 36839161, 2023). "In conclusion, ECE or DK attenuated Dexa-induced muscle atrophy by decreasing NLRP3 inflammasome formation and pyroptosis." (PMID 34360821, 2021). "This study evaluated the effects of ECE and DK on attenuating Dexa-induced muscle atrophy by decreasing NLRP3 inflammasome formation." (PMID 34360821, 2021). "We aimed to investigate if IL-1β activation via the Nlrp3 inflammasome is involved in inflammation-induced atrophy." (PMID 28097512, 2017). "HFD-induced testis atrophy was attenuated by NLRP3 knockout." (PMID 35915511, 2022).
disc degeneration (12 papers, 2017 to 2026). "Together, these data suggest that NLRP3 depletion in microglia reduces disc degeneration and associated pain." (PMID 36505450, 2022). "The effects of altering NLRP3 levels in microglia on disc degeneration and associated pain were examined in a mouse model for LDD." (PMID 36505450, 2022). "NLRP3‐mediated pyroptosis has been implicated in disc degeneration." (PMID 36600636, 2023). "The NLRP3/caspase-1/IL-1β axis has been found to be active in human lumbar cartilaginous endplate degeneration and their expression levels are positively associated with the grades of disc degeneration." (PMID 31383789, 2019). "Clinical analyses have shown markedly increased expression levels of pyroptosis-related markers, such as NLRP3, caspase-1, and IL-1β, in degenerated NP tissues, with these levels positively correlating with the severity of disc degeneration." (PMID 41056015, 2026). "For example, MCC950, a specific NLRP3 inhibitor, significantly slowed the progression of disc degeneration in animal models." (PMID 40688090, 2025). "In summary, signaling pathways such as NF-κB, MAPK, JAK-STAT, and NLRP3 inflammasome play critical roles in disc degeneration." (PMID 40688090, 2025). "The potential of NLRP3 inflammasome inhibitors in the treatment of disc degeneration is gradually becoming apparent." (PMID 40688090, 2025). "Protection from disc degeneration as a consequence of suppression of NF-kB-mediated NLRP3 inflammasome activation." (PMID 38255196, 2024). "For example, ASIC1a regulates nucleus pulposus cell pyroptosis via the NLRP3 inflammasome to promote intervertebral disc degeneration." (PMID 37246982, 2023). "To summarize, our data suggest that microglia-depletion of NLRP3 attenuates disc degeneration and reduces LDD-associated pain, while permanent activation of NLRP3 in microglia promotes disc degeneration and increases LDD-associated pain." (PMID 36505450, 2022). "To study the role of ASICs in the process of disc degeneration, we first examined the mRNA expression and protein levels of ASICs and NLRP3 inflammasome components such as NLRP3, caspase‐1, and IL‐1β in normal and degenerated disc tissues." (PMID 33111436, 2021). "The differential expression patterns of NLRP3, observed through comparative analysis of sham, vehicle-treated, and sLN-treated discs, underscore the potential of sLN as a modulator of inflammasome-mediated pathways in the context of disc degeneration." (PMID 39456246, 2024). "Surgical induction of LDD and the quantification of disc degeneration were performed, showing significant decreases in disc degeneration from Tmem119p-CreERT2; NLRP3 (fx/fx) mice and significant increases in disc degeneration from Tmem119p-CreERT2; NLRP3mut mice." (PMID 36505450, 2022). "A better understanding of the regulatory mechanisms between HCS-induced ER stress and its NLRP3 inflammasome-related response on AF cells may help us develop strategies to reduce ROS levels in AF cells, thereby preventing the development of disc degeneration." (PMID 35887297, 2022). "Thus, NLRP3 levels in disc microglia correlate with the pain and disc degeneration level in LDD patients." (PMID 36505450, 2022). "There is therefore a positive correlation for ASIC1a, ASIC3 and NLRP3 with disc degeneration." (PMID 33111436, 2021). "NLRP3 and cleaved‐caspase‐1 showed positive correlation with disc degeneration." (PMID 28224704, 2017). "According to a study on disc degeneration, METTL14 specifically induces the NLRP3 mRNA m6A modification and increases NLRP3 protein expression in the human osteosarcoma cell line U2OS." (PMID 38562618, 2024). "We hypothesize that sLN inhibits NLRP3 activation in NP cells through CD14 interaction, preventing disc degeneration progression." (PMID 39456246, 2024).
emphysema (12 papers, 2013 to 2026). "To further explore the mechanism how H2S protect against PM-caused emphysema and airway inflammation, we detected the change of ROS generation, NLRP3 inflammasome formation, and apoptosis." (PMID 32116706, 2020). "Furthermore, preclinical models demonstrate that NLRP3 deficiency attenuates cigarette smoke-induced emphysema and airway inflammation, highlighting the therapeutic potential of targeting this pathway." (PMID 41476973, 2025). "Our findings highlight IRF5 as a critical regulator of emphysema pathogenesis via NLRP3-mediated pyroptosis and Ly6Chigh-expressing immune cells." (PMID 41639423, 2026). "MCC950, a potent and specific NLRP3 inhibitor, significantly reduces inflammation and emphysema progression in cigarette smoke-exposed murine models by blocking NLRP3 ATPase activity and subsequent inflammasome assembly." (PMID 41476973, 2025). "STING activation can also lead to NLRP3-mediated pro-inflammatory cytokine production and secretion in emphysema and IPF." (PMID 37122745, 2023). "For example, NaHS administration prevented and partially reversed ozone-induced features of lung inflammation and emphysema via the regulation of the NLRP3-caspase-1, p38 MAPK, and Akt pathways." (PMID 36339716, 2022). "NLRP3-inflammasome expression was increased by CS extract and DEPs in both the normal and elastin-induced emphysema samples, and was suppressed by NAC." (PMID 34574829, 2021). "Recent studies showed that activation of NLRP3 inflammasome is important mechanism in PM-induced mice emphysema model." (PMID 32116706, 2020). "Mice emphysema, airway inflammation, and oxidative stress were evaluated, the expression of NLRP3, active caspase-1, and active caspase-3 were detected." (PMID 32116706, 2020). "Hydrogen sulfide played a protect role in PM-induced mice emphysema and airway inflammation by inhibiting NLRP3 inflammasome formation and apoptosis via Nrf2-dependent pathway." (PMID 32116706, 2020). "The protective effect of hydrogen sulfide on emphysema, airway inflammation, inhibiting oxidative stress, NLRP3 inflammasome formation, and anti-apoptosis was inhibited by Nrf2 knockout in mice." (PMID 32116706, 2020). "Both mtROS and NLRP3 inflammasome play a role in ozone-induced lung inflammation while only NLRP3 is involved in ozone-induced emphysema." (PMID 30466433, 2018). "We examined the importance of mtROS and NLRP3 inflammasome and their interactions in multiple ozone-induced lung inflammation and emphysema." (PMID 30466433, 2018). "The mouse model of elastase-induced emphysema depends on uric acid, NLRP3, ASC, IL-1R, and MyD88 as critical mediators of inflammation, alveolar wall destruction, and fibrosis." (PMID 24312100, 2013). "In addition to activating IFN I response, mtDNA and STING can also play a role in activating NLRP3 inflammasome, promoting IL-1β secretion and leading to emphysema and ILD." (PMID 37122745, 2023). "In addition, the NLRP3-inflammasome was activated by DEPs in ex vivo tissue explants from an elastase-induced emphysema animal model, and this activation was also suppressed by NAC." (PMID 34574829, 2021). "In this study, the NLRP3 inflammasome also played an important part in PM-induced emphysema and airway inflammation in vivo and in vitro with the results that the IL-1β expression, NLRP3, and active caspase-1 (p20) was enhanced in mice and A549 cells after PM exposure." (PMID 32116706, 2020). "Therefore, we hypothesize that H2S protect against PM-induced emphysema and airway inflammation via antioxidative stress, inactivation of NLRP3 inflammasome and anti-apoptosis through Nrf2-dependent pathway." (PMID 32116706, 2020). "The protective effect of H2S against particulate matter-induced emphysema and airway inflammation is exhibited via the Nrf2-dependent pathway through suppressing PYD domain-containing protein 3 (NLRP3) inflammasome formation and apoptosis." (PMID 36339716, 2022).
emphysema (continued). "The inflammasome complex also play a key role in pathogenesis of many diseases, NACHT, LRR, and PYD domains-containing protein 3 (NLRP3) inflammasome was the member of inflammasome that involved in airway disease including COPD and emphysema pathogenesis." (PMID 32116706, 2020). "The NLRP3 was also an important mechanism in cigarette smoking, ozone-induced mice COPD or emphysema." (PMID 32116706, 2020). "Phenotype-specific therapy selection may include NLRP3 inhibitors for frequent exacerbators, AIM2 inhibitors for emphysema-dominant patients, and IL-33 pathway modulators for chronic bronchitis phenotypes." (PMID 41476973, 2025). "Although IL-18 knockout mice exhibit reduced pulmonary inflammation and emphysema compared to wild-type mice after cigarette smoke, pulmonary inflammation occurred independent of NLRP3/caspase-1 axis after four weeks of cigarette smoke exposure." (PMID 28056996, 2017). "NLRP3 inflammasomes might also contribute to pathogenesis of chronic pulmonary disorders such as COPD and emphysema." (PMID 24312100, 2013). "Experimental studies in mice suggest activation of NLRP3 by some of those DAMPs might have important functions in the pathogenesis of ALI/ARDS, COPD/emphysema, and lung fibrosis." (PMID 24312100, 2013). "The data suggests that mtROS may not activate NLRP3 inflammasome-mediated ozone-induced emphysema." (PMID 30466433, 2018).
Familial cold urticaria (12 papers, 2012 to 2025). "Among the CAPS syndrome, there are familial cold urticaria (FCU) and Muckle-Wells syndrome which are also associated with NLRP3 mutations." (PMID 34434197, 2021).